PER1 (period circadian regulator 1)
Diseases named in the same sentence as PER1 in open-access papers (continued):
Sharing a sentence is not in itself a finding about the gene and the disease.
Obesity (32 papers, 2009 to 2025). Accumulation of substantial excess body fat. "To determine the role of Per1 in fat accumulation and obesity, we compared Per1-deficient mice to WT littermates fed a standard ND (10% kcal from fat) or a HFD (60% kcal from fat) for 8 weeks, respectively." (PMID 37209828, 2023). "Circadian Per1 controls daily fat absorption and accumulation, suggesting Per1 is a potential candidate of a key regulator in stress response and the relevant obesity risk." (PMID 37209828, 2023). "Mutation of the core clock gene Per1 that alters the phosphorylation site of PER1 results in a phase advance of food intake by several hours into the rest/sleep period and in obesity." (PMID 26082718, 2015). "Our Granger causality networks showed that multiple biological processes such as apoptosis, inflammation response and lipid metabolism are under circadian rhythm regulation and obesity causal genes are under circadian rhythm regulator PER1 in the fed networks." (PMID 20168994, 2010). "Some genes in this subnetwork, such as Arntl, Dbp, Per1, and Per2, are known to associate with obesity traits, while other genes, such as Map3k6 and Tsc22d3, represent novel factors." (PMID 19463160, 2009). "Thus, circadian Per1 is a potential candidate of a key regulator in stress response and the relevant obesity risk." (PMID 37209828, 2023). "Furthermore, the genes under PER1 regulation in the fed network are enriched for obesity causal genes." (PMID 20168994, 2010). "Consistent with previous reports, the present findings suggest that the genes linked to PER1-led oscillations may be exploited as novel points of intervention for obesity and other metabolic phenotypes." (PMID 19203388, 2009). "Specifically, the inactivation of the circadian rhythm regulator Per1 in mice prevents obesity on a high-fat diet." (PMID 38992336, 2024). "Abnormal expressions of PPP1CB and CSNK1E in obesity directly affect the core clock genes (PER1, PER2), and the accumulation of PERs and CRYs in the nucleus inhibits the transcription of CLOCK and BMAL1, disrupting energy homeostasis and leading to obesity." (PMID 39351493, 2024). "Another example is the triple Per mutant mice (Per1/Per2/Per3), which develop obesity when fed a high-fat diet (HFD)." (PMID 38818037, 2024). "Per1-knockout mice are protected from high-fat diet–induced obesity, which is accompanied by a reduction in the size of the bile acid pool, and the oral administration of bile acids restores fat absorption and accumulation." (PMID 37209828, 2023). "Per1/2/3 knockout mice are more likely to have obesity, which suggests that it regulates body weight." (PMID 35111358, 2022). "Obesity resulted in overall disruption of core clock genes (i.e., Bmal1, Clock, Rev-erbα/Nr1d1, Rev-erbβ/Nr1d2, Per1, Per2, Cry1, Cry2, Dbp and Rorα) in WAT." (PMID 35198059, 2022). "The relationship between circadian clock dysregulation and macrophage proinflammatory activation in diet-induced obesity was evaluated in a Per1ldc/Per2ldc mutant mice, characterized by disruption of the clock genes Per1 and Per2." (PMID 33371208, 2020). "The differential impact of obesity on clock gene expression in the gonadal and subcutaneous adipose depots was most pronounced in Rev-erbα, Per1 and Per2 gene expression profiles." (PMID 27439882, 2016). "Obesity with adipose accumulation reduces the amplitude of circadian gene expression by decreasing the peak expression of clock genes such as Per1 and Per2 in WAT of genetically obese mice." (PMID 25615603, 2015). "The present study was designed to determine the regulatory mechanisms of adipose Per1 in obesity and the possible relationship between adipose hypothermia and adipocyte function." (PMID 25397888, 2014). "The present in vivo animal study showed a significant downregulation of adipose Per1 mRNA level in obesity." (PMID 25397888, 2014).
Obesity (continued). "When the obesity causal genes were overlapped with the fasted and fed networks, 7 genes (ADA, BBS5, CBL, CCND3, FASN, FTO and SCARB1) overlapped with PER1's downstream genes in the fed network (Fisher's Exact Test p-value = 0.037)." (PMID 20168994, 2010). "Interestingly, Per1, Per2, and Cry2 expression is unchanged in obesity but alters in pregnant obese rats." (PMID 39083072, 2024). "Although it is unknown how Per1 and Per2 controls macrophage activation in obesity, the authors suggested a disruption in the feedback regulation of CLOCK/BMAL1 protein complex." (PMID 33371208, 2020). "Taurine normalized the gene and protein expression of PER1 in beta-cells, which suggests that it could be beneficial for the correction of daily rhythms and the amelioration of obesity and diabetes." (PMID 27857215, 2016). "A recently implicated gene in humans for obesity, FTO, is also part of the PER1 signature." (PMID 19203388, 2009). "The reduction in PER1 we observed after exercise is in contrast with a recent finding that a session of moderate-to-vigorous exercise (80% VO2max) increased the mRNA expression of PER1 in aSAT after 8-weeks of exercise training in adults with overweight/obesity." (PMID 40654849, 2025). "In the present study, conducted in a population of subjects with overweight/obesity, we observed an association between PM exposure measured in the week before the blood drawing and the methylation of circadian cycle genes (i.e., CLOCK, CRY1, CRY2, PER1, PER2, and PER3)." (PMID 33513987, 2021). "In humans with obesity, 24-h gene expression of CLOCK, BMAL1, PER1, CRY2, and REV-ERBα in adipocytes is disturbed." (PMID 35111358, 2022). "The present study aimed to evaluate the effects of PM2.5 and PM10 on the methylation profile of the clock genes ARNTL, CLOCK, CRY1, CRY2, PER1, PER2, and PER3 in a population of 200 women with obesity." (PMID 33513987, 2021). "The abundance of transcripts of HSD11B1, HSD11B2, PER1, and NR3C1 were unaffected by obesity or insulin." (PMID 33270115, 2021). "The 24 h pattern of clock genes showed that obesity alters the expression of CLOCK, BMAL1, PER1, CRY2 and REV-ERB ALPHA in adipocytes with changes found in CRY2 and REV-ERB ALPHA throughout the 24 h period." (PMID 25365257, 2014). "From a non-tumor perspective, PER1 is related to conditions such as Parkinson's disease, obesity, sleep, drug resistance, and premature ovarian insufficiency." (PMID 34220965, 2021). "Evidence was observed for effect modification from body mass index (BMI) regarding the PER1 gene: as PM2.5/10 increases, DNA methylation increases significantly for relatively low BMI values (BMI = 25), while it decreases in participants with severe obesity (BMI = 51)." (PMID 33513987, 2021). "In a time-course experiment with white adipose tissue biopsies from people with healthy weight or obesity or T2D, no variation in the rhythm and amplitude of core-clock (PER1, PER2, PER3, DBP, BMAL1, and CRY2), metabolic (PGC1), and clock-related (REVERB) genes could be observed in biopsy tissues." (PMID 37475884, 2023). "To determine the effect of the disrupted clocks on MetS components, we compared mRNA levels of Bmal1, Dec1, and Per1 in OSA patients with or without hyperglycemia, hypertension, hyperlipidemia, and obesity, which were considered as the major components of MetS." (PMID 36105285, 2022).
pancreatic cancer (31 papers, 2011 to 2025). "And ALKBH5 prevented pancreatic cancer progression by posttranscriptional activation of period circadian regulator 1 (PER1) in an m6A‐YTHDF2‐dependent manner." (PMID 40214031, 2025). "A tumor-suppressive effect of ALKBH5 was detected in pancreatic cancer by preventing its progression by activating period circadian regulator 1 (PER1), which in turn inhibited cell growth." (PMID 38503745, 2024). "Several studies have reported that the function of m6A methyltransferases in malignancies, as METTL3 accelerates pri-miR221/222 maturation to promote bladder cancer progression, ALKBH5 activates PER1 to inhibit pancreatic cancer progression." (PMID 37807062, 2023). "As an m6A eraser, ALKBH5 depletion increases m6A on PER1 mRNA, resulting in cell proliferation in pancreatic cancer, due to the decreased expression of PER1." (PMID 37015927, 2023). "In the cytokine signaling pathway, PER1 expression is suppressed by tumor necrosis factor (TNF)-α, and knockdown of PER1 decreases the proliferation of pancreatic carcinoma cells." (PMID 36385012, 2022). "Another study showed that demethylase ALKBH5 suppressed pancreatic cancer progression by post-transcriptional activation of PER1 in an m6A-YTHDF2-dependent manner." (PMID 34239358, 2021). "Previous research showed that demethylase ALKBH5 represses pancreatic cancer progression by up-regulating PER1 expression via m6A-YTHDF2-dependent pathway." (PMID 34916487, 2021). "Changes in expression levels of PER1 have been found in some cancers, including pancreatic cancer, oral squamous cell carcinoma, endometrial cancer, colorectal cancer, and non-small-cell carcinoma, but this has not been studied in OV." (PMID 34220965, 2021). "Contrary to this, other authors found higher expression of PER1 in pancreatic tumors vs. normal tissues." (PMID 33042011, 2020). "In particular, the PERIOD1 (PER1) gene has been recently proposed to be an anti-apoptotic factor in human pancreatic cancer cells." (PMID 24212620, 2011). "It inhibits pancreatic cancer cell growth by activating period circadian regulator 1 (PER1)." (PMID 40361322, 2025). "In addition, it is reported that ALKBH5 activates period circadian clock 1 (PER1), serving as a suppressor for pancreatic cancer in an m6A-YTHDF2 dependent way." (PMID 35804965, 2022). "Similarly, ALKBH5 also suppresses tumor progression in pancreatic cancer, lung cancer, and esophageal squamous cell carcinoma, with downstream targets such as PER1, YAP, and WIF-1." (PMID 35395767, 2022). "ALKBH5 was positively correlated with PER1 expression in pancreatic cancer tissues and could prevent pancreatic cancer progression by increasing PER1 mRNA expression in a m6A-dependent manner." (PMID 34697563, 2021). "Furthermore, its overexpression abolished m6A-YTHDF2 modification and post-transcriptionally activated PER1 to hinder the progression of pancreatic cancer." (PMID 34491904, 2021). "Especially PER1 and downstream effectors of the circadian clock are lower expressed in pancreatic cancer which further suggests they may act as tumor suppressor genes in healthy tissue." (PMID 27492458, 2016). "It was observed that one of the four human cytochrome P450-related genes, PER1 and DEC1, and downstream effectors, such as ubiquitin specific protease 30 were significantly under-expressed in pancreatic cancer." (PMID 33042011, 2020). "It has been demonstrated that clock genes, including PER1 and CRY2, are down-regulated, whereas ID2 is over-expressed in pancreatic cancers." (PMID 30934731, 2019).
pancreatic cancer (continued). "Moreover, the overexpression of PER1 and PER2 has been shown to impair tumor proliferation and induce apoptosis in lung, prostate, and pancreatic cancer, reinforcing the idea that the molecular clock machinery may be considered as a new therapeutic target." (PMID 29946530, 2018). "In addition, ALKBH5 posttranscriptionally activates period circadian regulator 1 (PER1) in an m6A-YTHDF2-dependent mechanism, with subsequent PER1 upregulation driving reactivation of the ATM–CHK2–CDC25C signaling cascade to suppress pancreatic cancer cell proliferation." (PMID 40986143, 2025). "Past works also report that PER-1 downregulation could be an important carcinogenic mechanism of PDAC; however, one study reported that this component appeared to be increased in pancreatic cancer tissue, possibly acting as an anti-apoptotic factor in pancreatic cancer cells." (PMID 39199335, 2024).
colon cancer (20 papers, 2013 to 2024). "It has been demonstrated that inhibition of Per1 caused reduced apoptosis in HCT116 colon cancer cells, while overexpression of Per1 leads to DNA damage-induced apoptosis." (PMID 27492458, 2016). "Over expression of Per1 in colon cancer cell lines was associated with a higher level of apoptosis after irradiation, whereas inhibition of Per1 expression led to a decrease in apoptosis." (PMID 25832911, 2015). "PER1 expression is diminished in a variety of malignancies, such as prostate cancer, colon cancer, cholangiocarcinoma, gastric cancer, and non-small cell lung cancer." (PMID 38245510, 2024). "Not only in SOC, the elevated proteins of PER1, AKAP12 and MMP17 are also associated with the migration and invasion in triple-negative breast cancer, melanoma and colon cancer." (PMID 37434173, 2023). "Our finding of negative regulation of Per1 in TIME of colon tumor provided evidence for BCL9-driven Wnt signaling role in circadian disruption." (PMID 34566638, 2021). "On the other hand, ectopic expression of PER1 was found to inhibit WEE1 expression in human colon cancer cell lines." (PMID 34221066, 2021). "Since we found that PER1 was the most significant downregulated genes when PER2 expression is low, the process may be related ATM/CHK2 as reported in a human colon cancer cell line." (PMID 33810377, 2021). "Also, ATM and CHK2 form a complex with circadian protein PER1, and it was further demonstrated that PER1 knockdown reduced ATM-mediated CHK2 phosphorylation and dampened apoptotic response to DNA damage in human colon cancer cell line HCT116 (Geryet al., 2006)." (PMID 39282509, 2023).
prostate carcinoma (18 papers, 2010 to 2025). A carcinoma that arises from epithelial cells of the prostate gland. "PER1 suppresses the androgen receptor’s transcriptional activity, and it appears that prostate cancer is partly caused by the clock gene’s downregulation." (PMID 38892035, 2024). "In a case-control study conducted in a Caucasian population, rs2289591 in PER1 (OR = 1.25; 95%CI: 1.00–1.57) was associated with more aggressive prostate cancer risk under a dominant genetic model." (PMID 36672368, 2023). "A previous study indicated that a missense variant of PER1 rs2585405 was associated with the susceptibility to prostate cancer." (PMID 34493277, 2021). "PER1 may modulate prostate cancer risk through its role in regulating DNA damage and cell growth by interacting with proteins in cell cycle pathways." (PMID 39062777, 2024). "More recently, alterations in other specific circadian rhythm gene pathways, specifically PER1 and PER3, were found to be associated with an increased risk of prostate cancer among all men." (PMID 40805144, 2025). "In prostate cancer, PER1 interacts with the androgen receptor (AR), serving as a negative regulator of AR activity." (PMID 41451215, 2025). "The other roles of PER1 include being regulated by androgens in the prostate, and the overexpression of PER1 can inhibit prostate cancer growth and induce cell death." (PMID 39062777, 2024). "Our findings extend previous studies showing that overexpression of Per1 and Per2 promotes apoptosis by altering the expression of apoptosis-related genes, including in prostate cancer cells." (PMID 25760074, 2015). "This is consistent with previous studies showing that Per1 is a tumor suppressor gene in non-small lung cell cancer and prostate cancer." (PMID 25760074, 2015). "In addition, PER1 has been reported to inhibit the transactivation of androgen receptor (AR) through direct interaction, and the ectopic expression of PER1 in human prostate cancer cells (LNCaP) reduces the expression of known AR target genes." (PMID 39012661, 2024). "However, the expression of Per1 in prostate cancer is significantly reduced, and overexpression of Per1 can inhibit cancer cell growth." (PMID 39011396, 2024). "Per1 is down-regulated in human prostate cancer samples compared to normal prostates." (PMID 20353609, 2010). "Moreover, over-expression of Per1 in prostate cancer cells has resulted in significant growth inhibition and apoptosis." (PMID 20353609, 2010). "PER1 and NPAS2 levels were related to all prostate cancers, while only RORA was significant for invasive tumors." (PMID 39011396, 2024). "PER genes are deregulated at many levels in cancer, such as altered methylation of PER1 and PER2 promoter and increased expression, for example, in prostate cancer, as PER1 is regulated by androgen receptor signaling." (PMID 36731029, 2023).